ACE (angiotensin I converting enzyme)
Diseases named in the same sentence as ACE in open-access papers (continued):
Sharing a sentence is not in itself a finding about the gene and the disease.
heart failure (continued). "It belongs in a class of drugscalled angiotensin converting enzyme (ACE) inhibitors which are used fortreating high bloodpressure and heart failure and forpreventing kidneyfailure due to high blood pressure anddiabetes." (PMID 20140081, 2009). "Thus the ability of ACE-inhibition and ARBs to counter this deleterious effect on the vascular phenotype could explain their beneficial effect, compared to other agents that decrease afterload, on morbidity and mortality in the treatment of heart failure." (PMID 19357768, 2009). "Thus, the ability of ACE-inhibitors and ARBs to modulate the vascular phenotype, to preserve normal flow mediated vasodilatation may explain the beneficial effects of these drugs compared to other forms of afterload reduction in the treatment of heart failure." (PMID 19357768, 2009). "When both therapies were combined in patients with heart failure in whom ACE inhibitor therapy was not sufficient, the addition of H/I appeared to have a positive effect on mortality and quality of life." (PMID 40846813, 2025). "Similarly, the Sudden Cardiac Death in Heart Failure Trial(SCD-HeFT) explicitly noted that all patients were on optimal medical therapy atthe time, which included beta-blockers, angiotensin-converting enzyme (ACE)inhibitors, and aldosterone antagonists." (PMID 40351668, 2025). "Until recently, no new drug reduced clinical events in patients with heart failure since the inception of angiotensin-converting enzyme (ACE) inhibition/angiotensin receptor blockers (ARB), beta-blockers, and aldosterone inhibitors." (PMID 40520225, 2025). "Treatment options using beta-blockers, ACE/angiotensin receptor blockers (ARB) inhibitors, aldosterone receptor antagonists, SGLT2 inhibitors, and diuretics (for volume control) are mandatory if features of heart failure are settled." (PMID 38910751, 2024). "Other important predictors of a higher MACE risk after PCI were non-radial access, heart failure and higher Killip class, albumin, CONUT score, ACE inhibitors, and GRACE score." (PMID 38609875, 2024). "In the meantime, substances like ACE-inhibitors, aldosterone antagonists, ARNI and, most recently, SGLT-2 inhibitors have revolutionized medical heart failure therapy, as they have been demonstrated to be able to reduce both heart-failure-related events and mortality." (PMID 38921673, 2024). "Guidelines recommend angiotensin-converting enzyme (ACE) inhibitors and beta-blockers (BBs) as standard therapy for all patients with symptomatic heart failure and reduced ejection fraction, regardless of the underlying etiology." (PMID 39791066, 2024). "In previous studies, ARNI significantly impacted LV function in heart failure patients, including those who failed to reach the target dose of either an ACE inhibitor or an ARB." (PMID 39301489, 2024). "Early initiation of angiotensin-converting enzyme (ACE) inhibitors slows the progression of the cardiomyopathy, and cardiomyopathy treatment and heart failure management in DMD largely relies on guideline-directed heart failure strategies." (PMID 38050701, 2024). "Thus, the combined inhibition of ACE and NEP is a new and promising approach to treat patients with hypertension, atherosclerosis, or heart failure." (PMID 37078106, 2023). "Furthermore, a previous study showed that ACE inhibitors, ARNI, ARB, or beta-blockers improve the 2-year survival of heart failure patients." (PMID 38201291, 2023). "Angiotensin-converting enzyme (ACE) Inhibitors and angiotensin receptor blockers (ARBs): These medications are prescribed in the early phase of STEMI to reduce ventricular remodeling, improve cardiac function, and prevent heart failure development." (PMID 37904413, 2023). "LEGEND-HTN found benefit for patients treated with thiazide or thiazide-like diuretics compared to angiotensin-converting enzyme (ACE) inhibitors in terms of three main outcomes of interest, i.e., acute myocardial infarction (MI), hospitalization with heart failure, and stroke." (PMID 36991144, 2023).
heart failure (continued). "Renin-angiotensin system inhibitors (RAS) inhibitors include angiotensin receptor blockers (ARBs) and angiotensin-converting enzyme (ACE) inhibitors decrease proteinuria, progression of chronic kidney disease (CKD), and protect against heart failure hospitalizations and cardiovascular events." (PMID 37214072, 2023). "Sacubitril‐valsartan, an inhibitor of the angiotensin receptor neprilysin (ARNi), has been purported to exhibit superiority over angiotensin converting enzyme (ACE) inhibitors and angiotensin receptor blockers (ARBs) in individuals diagnosed with heart failure." (PMID 38013641, 2023). "LV mechanical dyssynchrony causes by chronic RVP have been shown to be diminished with an ACE inhibitor in an animal model of heart failure but have not been previously shown to be of benefit in clinical cohort studies, although data are admittedly limited." (PMID 37124556, 2023). "The effects of ACE inhibitors on stable coronary artery disease without heart failure are controversial." (PMID 35313858, 2022). "Omapatrilat did not reduce mortality and hospitalization for heart failure compared with ACE inhibitors." (PMID 36101398, 2022). "The South African hospital NEML had 100% consistency with the WHO model EML for heart failure and antithrombotic medicines and the PHC NEML listed all foundation medicines for the treatment of heart failure (ACE inhibitors, beta-blockers, MRAs and loop diuretics)." (PMID 36482421, 2022). "Renin, ACE and AT1 receptors are important targets of anti-hypertensive and heart failure therapy." (PMID 35498160, 2021). "Thus, a major aim of this study was to compare the effect of ACE inhibitors and AT1 receptor blockers on systemic and particularly kidney hemodynamics during heart failure in normotensive and hypertensive rats." (PMID 33608612, 2021). "Pharmacological inhibition of AT1 receptor function by an ACE inhibitor, an AT1 receptor antagonist, or an ARNI (angiotensin receptor blocker and neprilysin inhibitor) is the mainstay of recommended prognosis-improving therapies of heart failure." (PMID 34576047, 2021). "Clinical studies utilizing patients with heart failure showed no statistical difference between ACE inhibitors and AT1 blockers on overall mortality." (PMID 33608612, 2021). "There are no RCTs to support a specific treatment and, therefore, all recommendations so far are based on expert opinions•Medical treatment: ° ACE inhibitor ° Medical (e.g., levosimendan) or device therapies (Impella or VA-ECMO) for heart failure/left ventricular dysfunction ° Consider β-blockers." (PMID 35237672, 2021). "To provide novel insights into the pathogenesis of heart failure-induced renal dysfunction, we compared the effects of ACE inhibitor (ACEi) and AT1 receptor blocker (ARB) on systemic and kidney hemodynamics during heart failure in normotensive HanSD and hypertensive transgenic (TGR) rats." (PMID 33608612, 2021). "Future studies will have to investigate whether inhibition of SCD could synergize with an ACE inhibitor or AT1 receptor antagonist to prevent detrimental and heart-failure-enhancing activities of SCD in patients with SCD-mediated pathologies." (PMID 34576047, 2021). "Only one of the 19 patients who were found to have an LVEF≤40% without previously having been diagnosed with a heart failure, received both beta-blockers and angiotensin-converting enzyme (ACE) inhibitors/angiotensin receptor blockers (ARB)." (PMID 32977752, 2020). "Recent studies performed on the same animal model of the heart failure (Tgαq*44 mice) demonstrated that the heart failure progression is indeed related to the activation of RAA system and activation of angiotensin converting enzyme/angiotensin II pathway (ACE/Ang II)." (PMID 32319199, 2020). "Lastly, heart failure patients are medically managed whereas our preclinical models do not receive a human standard of care (no beta-blockers, ACE inhibitors, etc)." (PMID 33253217, 2020).
heart failure (continued). "During the postpartum period, the standard heart failure therapy in PPCM, including beta-blockers, angiotensin-converting enzyme (ACE) inhibitors, angiotensin II receptor blockers (ARBS), mineralocorticoid receptor antagonists, and diuretics are recommended following delivery." (PMID 33042652, 2020). "For instance, the 2016 heart failure guideline of the European Society of Cardiology recommends close monitoring of creatinine, serum potassium, and urea upon ACE inhibitor therapy initiation, which was not similarly mentioned in the German ramipril SmPC." (PMID 30958278, 2019). "Diastolic heart failure is notoriously difficult to treat with little or no benefit from classical heart failure medication such as ACE inhibitors, angiotensin receptor blockers, aldosterone antagonists, or beta-blockers." (PMID 29889873, 2018). "It is likely that we missed a number of heart failure patients who use cardiac‐related drugs such as ACE‐inhibitors and beta‐blockers but no C01 drug, although only the most severe CVD cases will be included by using information on hospitalizations." (PMID 30220107, 2018). "As the RAS is known to be activated in heart failure patients, various therapeutic approaches involving RAS inhibition, including the use of angiotensin converting enzyme (ACE) inhibitors and angiotensin II receptor blockers (ARBs), have been developed in the past decades." (PMID 30092100, 2018). "Further, concomitant medication use in heart failure patients such as diuretics, ACE inhibitors and beta-blockers are not taken into account in the current heart failure animal models." (PMID 28475616, 2017). "Based on Rales Study and Ephesus Study, aldosterone antagonist is often complemented to angiotensin converting enzyme inhibitors (ACE-Is) or antagonists of angiotensin I (ARBs) treatment of congestive heart failure (CHF) and cardiac failure related to myocardial infaction." (PMID 28710615, 2017). "Subjects at greater risk of HHF aftertaking sitagliptin were those without severe hypoglycemia, without ACE inhibitorstreatment, with history of heart failure or receiving hemodialysis rather thanperitoneal dialysis." (PMID 27460913, 2016). "In conclusion, sitagliptin use was associated with an increased risk of HHF inpatients with T2DM receiving dialysis, especially in those without severehypoglycemia, without ACE inhibitors treatment, with prior heart failure orreceiving hemodialysis." (PMID 27460913, 2016). "To date, there is no meta-analysis comparing the efficacy of different ACE inhibitors in patients with heart failure." (PMID 26871774, 2016). "Clinically, one meta-analysis shows that ACE-inhibitors are less effective in reducing mortality in women with symptomatic heart failure than in men, whereas ACE-inhibitors do not modify the survival in women with asymptomatic heart failure." (PMID 25364906, 2014). "Conventional treatment consists of ACE inhibitors, angiotensin II receptor blockers, aldosterone antagonists and beta-blockers in case of heart failure, according to the ESC guidelines for heart failure." (PMID 24399323, 2014). "Angiotensin-converting enzyme (ACE) inhibition and aldosterone antagonism have shown a beneficial effect in cardiac failure by inhibiting the intracardiac RAAS, reduction in adrenergic tone, improvement in endothelial function, and prevention of myocardial fibrosis." (PMID 24818164, 2014). "Traditional heart failure therapies such as beta blockers, ACE inhibitors, and diuretics are not effective." (PMID 23533848, 2013). "Two large trials have evaluated the use of an aldosterone receptor antagonist in patients with heart failure in addition to an ACE inhibitor: the Randomized Aldactone Evaluation Study (RALES) and the Eplerenone Heart Failure Efficacy and Survival Study (EPHESUS)." (PMID 23476746, 2013).
heart failure (continued). "One study looking at functionally impaired older people without heart failure has shown that ACE inhibitors increase 6-minute walking distance to a degree comparable to that achieved after 6 months of exercise training." (PMID 22500226, 2012). "Although an increase in cardiac chymase activity has been reported in both clinical and experimental forms of heart failure, several studies suggest that in humans Ang II formation from Ang I is primarily dependent upon chymase rather than ACE." (PMID 22180785, 2011). "Combination therapy with ARBs and ACE inhibitors does not reduce mortality in patients with heart failure when compared to ACE inhibitor therapy alone." (PMID 20376345, 2010). "The other patient in heart failure responded to diuresis and continued ACE inhibition, and did not require inotropic support." (PMID 18298856, 2008). "A post hoc analysis of the PARADIGM-HF trial further suggests, to a certain extent, that lower doses of S/V can reduce heart failure-related mortality and morbidity compared to equivalent doses of ACE inhibitors, as it did not demonstrate a significant heterogeneity of treatment effect by dose." (PMID 40981086, 2025). "In the Effects of High-dose vs. Low-dose Losartan on Clinical Outcomes in Patients with Heart Failure (HEAAL) study, the authors performed a randomized, double-blind trial in 255 sites with 3,846 heart failure patients (30% women) with a NYHA class II-IV, LVEF ≤40% and an ACE inhibitor intolerance." (PMID 36937911, 2023). "Fourthly, there is no mention of race-based guidance for the use of ACE inhibitors in British NICE guidance such as in heart failure or post-myocardial infarction possibly as the cardio-protective rather than anti-hypertensive effect of prescribed medications is desired." (PMID 34508156, 2022). "Although perindopril has been reported to improve outcomes in patients with stable coronary heart disease without heart failure, the complicated interaction between ACE inhibitors and OSA might impair this effect." (PMID 35313858, 2022). "ASCO guidelines for monitoring and preventing cardiac dysfunction after doxorubicin therapy state that currently there is not sufficient evidence to recommend any single heart failure medication such as angiotensin-converting enzyme (ACE) inhibitors or beta blockers to improve function." (PMID 35096991, 2021). "Whilst heart failure medicines should be titrated to evidence-based target doses, we found that staff did not always agree with providing a target dose for ACE inhibitors, angiotensin receptor blockers, and/or beta-blockers in the patient’s fold-out medicines chart." (PMID 33766141, 2021). "The most frequent PPO was in 31.1% of patients, who were prescribed regular opioids without a laxative, 6.9% had osteoporosis but were not prescribed bone anti-resorptives, 5.7% had heart failure or coronary artery disease but were not prescribed angiotensin converting enzyme inhibitors (ACE)." (PMID 32545451, 2020). "The higher prevalence of heart failure in the β-group, or the higher prevalence of hypotension in the no-β-group, may explain the higher prescription rate of ACE inhibitors in the β-group." (PMID 32272880, 2020). "Furthermore, studies have shown that early administration of angiotensin-converting enzyme (ACE)-inhibitors and beta blockers reduce LV dysfunction and cardiac events including sudden death, any cardiac death, and symptomatic heart failure in patients that received high dose doxorubicin." (PMID 32714566, 2020). "Thus, it is possible that TAK-272 could show more potent cardioprotective effect than other RAS inhibitors, an ACE inhibitor or an ARB, in clinical study, and TAK-272 become a first-line RAS inhibitor for the treatment of heart failure." (PMID 30092100, 2018). "Those patients experiencing significant declines in LVEF are treated with standard heart failure medications such as beta blockers or ACE inhibitors, and if LVEF does not recover, trastuzumab may be withheld." (PMID 28101782, 2017).
heart failure (continued). "However, some recent trials have demonstrated that it does not significantly improve the heart failure patients’ prognosis when used alone or combined with ACE inhibitors." (PMID 29152151, 2017). "Recent studies and our current findings suggest that components of Wild garlic (Allium ursinum, AU) may play a role in reducing blood pressure, inhibiting angiotensin-converting enzyme (ACE), as well as improving right ventricle function in rabbit models with heart failure." (PMID 28677661, 2017). "Furthermore, a recent study has also verified that the ACE inhibitor perindopril enhanced exercise functional capacity in elderly people without heart failure and maintained health-related quality of life." (PMID 24391595, 2013). "The administrative data sets used in this study contained no information on the medical management of heart failure, in particular use of drugs such as ACE inhibitors, angiotensin receptor blockers and beta-blockers that have been shown to improve long-term survival." (PMID 22533631, 2012). "However, we would like to emphasis that the concerns about ACEI and anemia should not keep physicians from using ACE inhibitors in their management of heart failure." (PMID 16515712, 2006). "Unlike ACE inhibitors, ARBs, a class of medication that has been used to lower blood pressure and reduce proteinuria, left ventricular hypertrophy, and improve outcomes in heart failure, do not affect bradykinin levels but instead block the action of angiotensin II." (PMID 40636633, 2025). "Finally, potential unmeasured bias, including the absence of detailed information on heart failure medications such as ACE inhibitors, ARBs, MRAs, and diuretics, may have influenced the findings of this study." (PMID 41312157, 2025). "In addition, classic RAS blockers, such as angiotensin converting enzyme inhibitors (ACE-Is) and angiotensin receptor inhibitors (ARBs), may prevent AF by affecting the accumulation of EFT, especially in patients with heart failure and known left heart failure." (PMID 36213458, 2022). "Interestingly, inconsistencies with the treatment guidelines were found in 58.3% of all patients with heart failure, especially regarding the lack of the most advisable treatment strategy, which can have an impact on final patient-survival (e.g. β-blockers and ACE-inhibitors or ARBs)." (PMID 30760276, 2019). "In the ATMOSPHERE study, which was the largest clinical trial to evaluate the cardioprotective effect of aliskiren in heart failure with reduced ejection fraction patients, aliskiren failed to meet the prespecified criteria for noninferiority to an evidence-based dose of enalapril, an ACE inhibitor." (PMID 30092100, 2018). "In addition, studies have shown that ACE-inhibitors, or ACE-inhibitors in combination with beta-blockers, delay the progression of cardiomyopathy in patients with Duchenne muscular dystrophy (DMD), and has a beneficial effect on long-term survival of DMD patients with heart failure." (PMID 25086734, 2014). "However, both meta-analyses focussed on adverse effects associated with combination therapy and did not address outcomes such as readmission for heart failure or mortality where combination therapy may offer a benefit over ACE inhibitor therapy alone." (PMID 20376345, 2010). "Beta blockers were prescribed to 54.1% of the patients, 48.8% received diuretics, 31.6% got ACE inhibitors and 11.0% were treated by AT1 receptor antagonists, but 5.1% of the patients did not receive any heart-failure specific medication prescription." (PMID 40343234, 2025). "In addition afterload-reducing agents like ACE inhibitors to reduce right ventricular filling pressure and to increase cardiac output in patients with significant tricuspid regurgitation should become standard after atrial switch procedure, irrespective of heart failure symptoms." (PMID 37505269, 2023).